NLRP3 (NLR family pyrin domain containing 3)
Diseases named in the same sentence as NLRP3 in open-access papers (continued):
Sharing a sentence is not in itself a finding about the gene and the disease.
colitis (continued). "In the present study, we reported for the first time that orally-administered RA-loaded niosomes markedly reduced inflammasome-related proteins such as NLRP3, ASC and caspase-1 in a DSS-induced colitis experimental model in mice." (PMID 33530569, 2021). "The major components and effector molecules of the inflammasome, such as NLRP3, ASC, AIM2, Caspase 1, Caspase 11, IL-18, and IL-1β, play important roles in DSS-induced colitis." (PMID 34721422, 2021). "We also found that Xi Lei San significantly inhibited NLRP3 inflammasome activity, reduced the levels of inflammatory cytokines, and suppressed autophagy in DSS-induced colitis model rats." (PMID 33967625, 2021). "The outcome from this study supports the statement that curcumin suppresses the activation of NLRP3 and ameliorates DSS-induced colitis in mice." (PMID 33918207, 2021). "It has previously been shown that DMF suppresses NLRP3 inflammasome in THP-1 cells and the dextran sulfate sodium-induced experimental colitis model." (PMID 34858398, 2021). "hucMSC-derived exosomes carrying miR-378a-5p inhibited NLRP3 inflammasomes and abrogated cell pyroptosis to protect against DSS-induced colitis." (PMID 34294138, 2021). "Nod-like receptor family pyrin domain-1 containing 3 (NLRP3) are the pattern-recognition receptors (PRR) that constitute inflammasomes, with a major part in the development of colitis via secreting pro-inflammatory cytokines." (PMID 33182623, 2020). "In addition, IL-37 in vivo could inhibit NLRP3 activation also in colitis- and LPS-induced disease." (PMID 32849879, 2020). "This study found that Jmdjd3 promoted NLRP3 inflammasome regulation and exacerbated DSS-induced colitis in mice." (PMID 32456012, 2020). "Nlrp3-/- mice, treated with DSS, show reduced pro-inflammatory cytokine expression and develop less severe colitis, as compared with WT mice." (PMID 32545788, 2020). "Following treatment with 10 mg/kg and 50 mg/kg sinapic acid, the protein levels of NLRP3, ASC, IL-1β, and caspase-1 were reduced in colitis mice." (PMID 33312339, 2020). "Emerging evidence suggests the pivotal role of NLRP3 inflammasome in the development and pathogenesis of IBD and NLRP3 –/– mice were protected in experimental colitis." (PMID 32945118, 2020). "Dietary fiber and SCFA acted on G-protein coupled receptor GPR43 of colonic epithelial cells to activate the NLRP3 inflammasome and further ameliorate DSS-induced colitis through IL-18-mediated gut homeostasis." (PMID 33227973, 2020). "DSS treatment significantly induced increases in the protein levels of NLRP3, ASC, IL-1β, and caspase-1 in the colons of the colitis mice." (PMID 33312339, 2020). "There is a large body of evidence that natural compounds targeting NLRP3 are able to exert anti-inflammatory effects on dextran sulphate sodium (DSS)-induced colitis in mice and colitis induced by 2,4,6-trinitrobenzenesulfonic acid (TNBS) in rats." (PMID 31200447, 2019). "Exposure to even low doses of Al (1.5 mg/kg) has been shown to aggravate intestinal damage in mouse colitis models, such as worsening of colitis and upregulation of the mRNA expression of inflammatory cytokines IL1β, IL17A, and Nlrp3." (PMID 31523502, 2019). "Previous studies showed that the NLRP3 inflammasome contributes to the severity of DSS-induced acute colitis and inherited spontaneous colitis." (PMID 30823406, 2019). "In an acute colitis mouse model induced by DSS, NLRP3 gene knockout and medical inhibition of the NLRP3 inflammasome activation both exerted protective effects on mice." (PMID 29888292, 2018). "In an acute colitis model in mice induced by dextran sulfate sodium (DSS), NLRP3 gene knockout or medical inhibition of the NLRP3 inflammasome activation both exerted protective effects on mice." (PMID 29507526, 2018). "Activation of the NLRP3 inflammasome has been shown to critically maintain epithelial integrity in the colon and attenuate DSS-induced colitis in mice." (PMID 30382081, 2018).
colitis (continued). "A recent report suggested that defective signaling of IL-10, an anti-inflammatory cytokine, in a lipopolysaccharide-induced colitis of mice and in macrophages of IBD patients led to dysregulated activation of the NLRP3 inflammasome and production of IL-1β31." (PMID 29773794, 2018). "Consistently, hydrocotarnine can enhance IL-18 secretion in response to NLRP3 inflammasome activation in vitro and enhance IL-18 secretion in vivo in the colon of mice with DSS-induced colitis." (PMID 30382081, 2018). "Taken together, our data demonstrated that modulation of ROS by procyanidin provided a potential method for colitis treatment, downregulating the expression of MMP9, the activation of NF-κB signaling, and the NLRP3 inflammasome at the same time." (PMID 29354126, 2017). "We found that oral administration of DSS in NLRP3−/− mice induced a less severe colitis than WT mice and produced lower levels of MPO and IL-1β in colonic tissues, which suggested the important role of NLRP3 inflammasome in DSS-induced colitis." (PMID 28553294, 2017). "Our study provided evidence for the first time that baicalein attenuated TNBS-induced colitis, at least in part, via inhibition of TLR4/MyD88 signaling cascade as well as inactivation of NLRP3 inflammasome." (PMID 29180692, 2017). "In this study, we investigated the role of the NLRP3 inflammasome in the development of UC using human UC operation resection specimens and an OXA-induced colitis model." (PMID 27966619, 2016). "Thus, NLRP3 could exert its protection roles when colitis was initiated." (PMID 27929086, 2016). "In our previous characterization of the Nlrp3−/− mice, we reported that these mice exhibited reduced colonic IL-10 expression during the inflammatory phase of DSS-induced colitis." (PMID 27610005, 2016). "Consistently, our results demonstrated that autophagy contributed to CB2R-mediated inhibition of NLRP3 inflammasome initiation and activation in peritoneal macrophages stimulated with LPS/DSS as well as in a mouse model of DSS-induced colitis." (PMID 27611972, 2016). "Here we investigated the role of CB2R in NLRP3 inflammasome activation in macrophages and explored its relevance to dextran sulphate sodium (DSS)-induced experimental colitis." (PMID 27611972, 2016). "Compared with the vehicle group, treatment with HU 308 (1 mg/kg, i.p.)significantly decreased NLRP3, the Casp-1 p20/Casp-1 p45 ratio and proIL-1β in colon from DSS-induced colitis mice." (PMID 27611972, 2016). "Colitis was induced by OXA treatment in NLRP3−/− mice and caspase-1−/− mice to determine the involvement of NLRP3 and caspase-1 in this disease process." (PMID 27966619, 2016). "Collectively, these data indicated that TRIM31 played crucial roles in limiting NLRP3 expression and thus exacerbated DSS-induced colitis." (PMID 27929086, 2016). "Our study herein provides molecular insights into how the IL-10/IL-10R signaling axis regulates NLRP3 inflammasome activation in macrophages during acute and chronic LPS/ATP stimulation, and helps to identify novel targets that could be exploited to treat colitis." (PMID 26412089, 2015). "During colitis, the dissociated TXNIP was bound to NLRP3, and this interaction was blocked by MitoQ treatment." (PMID 23915129, 2013). "In the present study, we showed that MitoQ suppresses ROS-promoted dissociation of TXNIP from TRX, inhibits the interaction between TXNIP and NLRP3, and significantly decreases levels of IL-1 beta and IL-18 in the colons of mice with DSS-induced colitis." (PMID 23915129, 2013). "Similarly, in DSS-induced colitis, MHV-68 infection resulted in significant expression of GSDMD, NLRP3, IL-1β, and IL-18 in peritoneal macrophages." (PMID 40041420, 2025). "Isobutyric acid pretreatment significantly downregulated pro-inflammatory gene expression (IL-1β, TNF-α, NLRP3, and ASC) while upregulating tight junction components (occludin, claudin-1, and zo-1), demonstrating its protective role against DSS-induced colitis." (PMID 41171006, 2025).
colitis (continued). "On one hand, absence of NLRP3 inflammasomes and caspase-1 has been shown to increase the inclination of mice towards developing colitis in response to DSS, even leading to mortality." (PMID 40041420, 2025). "The findings of the present study demonstrated that these genera exhibited significant correlations not only with conventional phenotypic indicators of colitis, but also with body inflammation, intestinal barrier function, and the LPS/TLR4/NF-κB/NLRP3 signaling pathway." (PMID 40130239, 2025). "Inflammasome activation and the progression of inflammatory bowel disease are modulated by palmitoylation of NLRP3, while inflammasome activation and the severity of dextran sulfate sodium (DSS)-induced colitis in mice are effectively attenuated by pharmacological inhibition of NLRP3 palmitoylation." (PMID 40959086, 2025). "Using wild-type (WT) and NLRP3 knockout (Nlrp3-/-) mice, we demonstrated that GB1 administration significantly ameliorated colitis symptoms, as evidenced by improved body weight, disease activity index (DAI) scores, colon length, and histological damage in WT mice." (PMID 40362256, 2025). "Overall, ATF could inhibit the activation of the NF-κB/NLRP3 signaling pathway and to reduce the expression of colonic inflammatory mediators, thereby ameliorating DSS-induced colonic inflammation." (PMID 40130239, 2025). "Dysbiosis is linked to both the NLRP3 and the NLRP6 inflammasome, and mice lacking NLRP3 or NLRP6 exhibit aggravated colitis." (PMID 40796700, 2025). "It inhibits NLRP3 activation and oxidative stress in conditions such as colitis and arthritis, but its role in ORG and P2X7R/NLRP3 regulation remains unclear." (PMID 41586196, 2025). "Secondly, our study did not incorporate the use of pyroptosis inhibitors, such as the NLRP3 inflammasome inhibitor MCC950, to assess whether the suppression of pyroptosis could mitigate MHV-68-induced colitis." (PMID 40041420, 2025). "The results showed that VANGL2 did not affect NLRP3 inflammasome activation and colitis progression in March8-W110A mice compared to March8-WT mice." (PMID 39899477, 2025). "In colitis, CYBB cooperates with TLR4 to regulate the activation of the NLRP3 inflammasome." (PMID 40692778, 2025). "Several experimental studies have investigated the therapeutic potential of PTX in models of colitis; however, the present study is the first to elucidate its modulatory effects on the SPHK1/S1P, IL‐6/STAT3, AMPK/mTOR/NLRP3, and ZO‐1 signaling pathways in experimental colitis." (PMID 40387460, 2025). "Evodiamine, a natural product, inhibits NLRP3 inflammasome assembly to activate cellular autophagy, attenuates experimental DSS-induced colitis injury, and suppresses NLRP3 inflammasome by inhibiting apoptosis-associated speckle-like protein oligomerization and caspase-1 activity in macrophages." (PMID 40842999, 2025). "The heat map, volcano map, and GSEA enrichment graph suggested that NLRP3, as a differentially expressed gene, could play a crucial role in UFA1-promoted inflammation progression in the mouse model of colitis." (PMID 39966502, 2025). "The Nlrp3 inflammasome mediates intestinal inflammation in UC by sensing stress, promoting the secretion of IL-1β and IL-18, epithelial damage, and immune activation, and is upregulated in DSS-induced colitis." (PMID 40995471, 2025). "Thus, NLRP3 protein expression level was determined and it was found that UAF1 inhibitor markedly restrained NLRP3 protein expression level in colon tissue of colitis mice (P < 0.05)." (PMID 39966502, 2025). "Notably, these protective effects were abolished in Nlrp3-/- mice, confirming the essential role of NLRP3 in GB1-mediated mitigation of colitis." (PMID 40362256, 2025). "Studies demonstrate that the activation of NLRP3 may improve the prognosis of IBDs-mice infected with H. pylori, which exhibits less severity of DSS-induced colitis, and characterized by notably reduced inflammation and less epithelial alterations." (PMID 39569001, 2024).
colitis (continued). "A severe enhancement in acute and recurrent colitis as well as the progression of CAC was observed in rodents lacking NLRP3, Pycard, and Casp-1, which was partially induced by suppressed IL1 and IL18." (PMID 38892354, 2024). "In contrast, the deleterious effect of Cth deletion on the pro-inflammatory response, including NLRP3 inflammasome activation and innate cytokine production, has been also reported; unfortunately, histological colitis was not investigated in this study." (PMID 39427081, 2024). "Accumulating evidence have suggested that low levels of NLRP3 reduce DSS‐colitis and TNBS‐colitis." (PMID 39119947, 2024). "In DSS‐induced colitis, hydroxysafflor yellow A was found to increase Proteobacteria and Escherichia–Shigella, while reducing Bacteroidetes and Enterococcaceae, and inhibiting GSDMD‐mediated pyroptosis and NLRP3 inflammasome signaling pathways." (PMID 39568773, 2024). "On the contrary, Alhagi/MSC significantly downregulated the expression of apoptosis and inflammasome-related proteins, such as NLRP3, BAX, and Caspase3 levels, and weakened the TUNEL positive signal in DSS-induced mouse colitis models, while it increased the PCNA expression levels." (PMID 38612465, 2024). "In this study, we aimed to investigate the anti-colitis efficacy of CSCC and explore whether and how Gpr43 inhibits the STAT3/NLRP3 signaling pathway, thereby mediating the protective effects of CSCC on the intestinal barrier." (PMID 39329121, 2024). "In experimental colitis mouse models, REV-ERBα demonstrates significant anti-inflammatory properties by specifically inhibiting NF-κB and Nlrp3 expression, effectively reducing Nlrp3 inflammasome activity." (PMID 39456709, 2024). "Further, the NLRP3-mediated inflammasome activity was inhibited based on results showed that DCA was able to reduce expression level of cleaved caspase-1 and inhibit the activation of IL-1β in colitis-induced mouse model." (PMID 37902927, 2024). "Another study illustrated that baicalein could alleviate colitis symptoms by inhibiting the TLR4/MyD88 signaling cascade and activating the NLRP3 in mice." (PMID 39421730, 2024). "The mechanisms through which CSCC protects against DSS-induced colitis may include upregulating Gpr43, inhibiting the STAT3/NLRP3 pathway, and suppressing inflammation factors like IL-17A." (PMID 39329121, 2024). "The results first revealed that MC-LR, through NLRP3 inflammasome-mediated pyroptosis, may induce colitis and even IBD, and it could aggravate DSS-induced colitis in the same way." (PMID 37505716, 2023). "This is consistent with the previous finding that formononetin administration attenuates colitis by inhibiting the NLRP3 inflammasome signaling pathway." (PMID 37370098, 2023). "Aberrant NLRP3 inflammasome activation involves the participation of varied components including ASC and Caspase-1 which contribute to the development of IBDs, including colitis." (PMID 37233492, 2023). "Agonist-mediated activation of cannabinoid receptor 2, a G protein-coupled receptor primarily located on immune cells, that inhibits NLRP3 inflammasome activation and alleviates DSS-induced colitis in mice by increasing autophagy, has been used in clinical treatment of IBD." (PMID 37152076, 2023). "In addition, the TNBS-induced C57BL/6 mice model of colitis presented decreased c-Casp3, BAX/BCL-2, c-Casp9, NLRP3, ASC, c-Casp1, GSDMD, IL-18, high mobility group box 1 (HMGB1), NF-κB, ERK, p38, and JNK." (PMID 37367886, 2023). "For example, agonist-mediated activation of G-protein-coupled receptors (GPCRs) may inhibit the NLRP3 inflammasome activation, which could attenuate the DSS-induced colitis in mice." (PMID 37298868, 2023). "Others also demonstrate that inhibiting ILK abrogates NLRP3-mediated IL-1β production, that ILK knockdown reduces TNF-α production via NF-κB, and that ILK knockout in intestinal epithelial or myeloid cells reduces DSS-induced colitis in mice." (PMID 36930690, 2023).
colitis (continued). "In addition, the TNBS-induced Sprague-Dawley mice model of colitis presented decreased IL-1β, IL-6, IL-12, caspase-1, caspase-3, TXNIP, and NLRP3 levels." (PMID 37367886, 2023). "In conclusion, our research is the first to show that MC-LR may induce colitis, and even IBD, through NLRP3 inflammasome-mediated pyroptosis, and it could aggravate DSS-induced colitis in the same way." (PMID 37505716, 2023). "Both Caspase-1−/− and NLRP3−/− mice have impaired epithelial proliferation and increased mucosal permeability accompanied by defective healing responses to mucosal damage during DSS-induced colitis." (PMID 37519301, 2023). "Chlorogenic acid mitigated colitis by reducing M1 macrophage polarization through suppression of pyruvate kinase M 2 (Pkm2)-dependent glycolysis and inhibition of NOD-like receptor protein 3 (Nlrp3) activation." (PMID 37813835, 2023). "Overall, the aim of this present study is to explore the anti-inflammatory effects of a polyphenolic extract rich in anthocyanins from Aristotelia chilensis through inhibition of NLRP3 inflammasome and MC activation using an animal model of TNBS-induced CD-like colitis." (PMID 38283356, 2023). "For instance, curcumin or melatonin have been shown to inhibit NLRP3 inflammasome and TLR4/MyD88/NF-κB signaling pathway respectively, reducing abdominal pain as well as acting like immune checkpoints in preclinical models of colitis." (PMID 37233492, 2023). "Oral QT-loaded silk fibroin nanoparticles (QSFN) can produce obvious intestinal anti-inflammatory properties by down regulating proinflammatory cytokines (TNF-α, IL-1β, IL-6, MCP-1, ICAM-1, NLRP3, iNOS) and significantly reducing the DAI score of DSS-induced colitis mice." (PMID 37033644, 2023). "Numerous studies have revealed that the nucleotide-binding domain-like receptor family pyrin domain containing 3 (NLRP3) inflammasome plays a pivotal role in the pathogenesis of IBD, and inhibition of the NLRP3 inflammasome alleviates colitis in experimental animals." (PMID 35330829, 2022). "The researchers showed that NOR alleviated colitis and reduced the levels of NLRP3, cleaved caspase-1 and IL-1β in colons of the mice." (PMID 36090968, 2022). "It has been reported Panax ginseng polysaccharides (GPS) relieved the DAI, colon length shortening, and pathological changes in colonic tissue in mice with colitis, while adjusting oxidative level and inflammatory cytokines through inhibiting the JAK2/STAT1/NLRP3 pathway." (PMID 35327312, 2022). "Moreover, existing studies suggest that repressing NLRP3 inflammasome can ameliorate intestinal inflammatory injury as well as CPT-11-induced colitis." (PMID 35712724, 2022). "Whilst S100A8 and S100A9 may play a central role in propagating neuroinflammation in colitis models, it has been suggested that NLR family pyrin domain containing 3 (NLRP3) protein activation may be involved." (PMID 34983592, 2022). "NLRP3 serves as one of the core components of the NLRP3 inflammasome, and we hypothesize that BAFF affects the NLRP3 inflammasome in mice with colitis." (PMID 35320937, 2022). "NLRP3 gene knockout mice are protected from dextran sodium sulfate (DSS) or 2,4,6-trinitrobenzene sulfonic acid (TNBS) induced colitis compared to wild-type animals." (PMID 35722277, 2022). "Interestingly, polysaccharide from Scutellaria Baicalensis Georgi (SBG) also has anti-NF-κB effects, through which it inhibits NLRP3 inflammasome activation and mitigates DSS induced colitis." (PMID 36090968, 2022). "OLT1177, a selective inhibitor of NLRP3 inflammasomes, was administered during the induction period of DSS-induced mice to alleviate the disease phenotype, and OLT1177 was effective in preventing the onset of DSS colitis." (PMID 36145301, 2022). "In addition, our study found that Forsythia suspensa extract can inhibit the protein and gene expression levels of NLRP3, ASC, Caspase-1 and GSDMD in colitis mice." (PMID 35326124, 2022).